CCN1 (cellular communication network factor 1)
Diseases named in the same sentence as CCN1 in open-access papers (continued):
Sharing a sentence is not in itself a finding about the gene and the disease.
cholestasis (2 papers, 2018 to 2022). Impairment of the bile flow caused by obstruction within the liver, or outside the liver in the bile duct system. "In response to cholestasis, CCN1 induces the activation of NF-κB through interaction with integrins αvβ3/αvβ5 to induce the expression of Jag1, which in turn activates NOTCH1 to induce cholangiocyte proliferation." (PMID 35708907, 2022).
diabetic nephropathy (2 papers, 2020 to 2025). "In kidney disease, such as IgA nephropathy, diabetic nephropathy, and membranous nephropathy, CCN1 expression was significantly downregulated in podocytes, especially when there was substantial mesangial expansion." (PMID 40076566, 2025).
emphysema (2 papers, 2021 to 2022). "Interestingly, the progressive increase in cCNN1 during CS exposure induced MMP1 secretion while decreasing that of VEGF, implying a role for CCN1 in elevating MMP1 and down-regulating VEGF, alterations which have been well documented in inducing emphysema." (PMID 36613669, 2022).
infarction (2 papers, 2021 to 2024). A localised pathological necrosis of tissue resulting from obstruction of the blood supply usually by a thrombus, an embolus, or vascular torsion. "The expression levels of inflammatory cytokines TNF-α, IL-1β, and CCN1 in the peri-infarction cortex showed an increase post-I/R, a decrease post-TGN-020 treatment, and a subsequent increase following ERK1/2 pathway activation." (PMID 37695472, 2024). "When the treatments began 36–48 h after infarction, only CCN1/CYR61 was reduced, highlighting the importance of understanding the time frames for effective therapeutic intervention." (PMID 34063397, 2021).
influenza (2 papers, 2020). An acute viral infection of the respiratory tract, occurring in isolated cases, in epidemics, or in pandemics; it is caused by serologically different strains of viruses (influenzaviruses) designated A, B, and C, has a 3-day incubation period, and usually lasts for 3 to 10 days. "As a pro-inflammatory factor, CCN1 expression can be enhanced by CVB3, oncolytic herpes simplex virus-1(HSV-1)and influenza A virus (IAV) infection." (PMID 31957543, 2020).
Listeria infection (2 papers, 2021 to 2022). "However, the role of CCN1 protein and its interaction with TLR2/4 pathways in intestinal epithelial cells was not elucidated after Listeria monocytogenes infection." (PMID 35269881, 2022).
myocardial ischemia (2 papers, 2019 to 2022). A disorder of cardiac function caused by insufficient blood flow to the muscle tissue of the heart. "Similar to CCN2, myocardial CCN1 and CCN4 also respond as immediate early genes and reach peak levels of expression during the inflammatory phase after onset of myocardial ischemia." (PMID 34854055, 2022).
retinopathy of prematurity (2 papers, 2017 to 2024). A bilateral retinopathy characterized by neovascularization, scarring, retinal detachment, and eventually blindness. "To determine whether the expression and tissue distribution of CCN1 is altered in response to ischemic insult, we used a mouse model of oxygen-induced retinopathy (OIR), which recapitulates key aspects of the neovascular response seen in humans with retinopathy of prematurity (ROP)." (PMID 28469167, 2017).
steatosis (2 papers, 2020 to 2023). Increased lipid within the cytoplasm of cells. "In vitro analysis revealed that CCN1 increased the intracellular TG content, the pro-inflammatory cytokines and the expression level of apoptosis-associated proteins in a steatosis model using murine primary hepatocytes." (PMID 32081971, 2020). "In order to determine if the effect of CCN1 in inducing steatosis depended on promoting inflammation, we isolated and cultured murine primary hepatocytes in vitro." (PMID 32081971, 2020). "Controlling the expression of CCN1 in murine NASH models demonstrated that CCN1 increased the severity of steatosis and inflammation." (PMID 32081971, 2020). "H&E staining and oil red O staining revealed that Ad-CCN1 mice developed more steatosis when fed a HF diet for 11 weeks." (PMID 32081971, 2020). "CCN1 upregulation was found to be closely related with steatosis in patients with NASH, obese mice and a FFA-treated hepatocyte model." (PMID 32081971, 2020). "In our study, we found that CCN1 was correlated with steatosis in patients with NASH." (PMID 32081971, 2020). "We investigated the role of CCN1 in the pathogenesis of steatosis in a murine and cellular model." (PMID 32081971, 2020). "Together, these results suggest that overexpression of CCN1 increases the severity of steatosis." (PMID 32081971, 2020). "We conclude that increased CCN1 may act as an initiation factor in steatosis in NASH." (PMID 32081971, 2020). "In order to demonstrate the role of CCN1 in the pathogenesis of steatosis, we controlled its expression by delivering adenoviruses (Ad) expressing GFP or CCN1 into mice through tail vein injection." (PMID 32081971, 2020). "In order to explore the role of CCN1 in NASH, we analysed the relationship between CCN1 and the severity of NASH expressed by the NAFLD activity score (NAS), which comprises the grade of steatosis, lobular inflammation and balloon degeneration." (PMID 32081971, 2020). "Most importantly, hepatic CCN1 is positively correlated with NAS and steatosis." (PMID 32081971, 2020).
airway hyperresponsiveness (1 paper, 2026). "Knockdown of CCN1 attenuated airway hyperresponsiveness, remodeling, and EMT, whereas exogenous CCN1 administration exacerbated these pathologies." (PMID 41559741, 2026).
alcoholic liver diseases (1 paper, 2022). A disorder caused by damage to the liver parenchyma due to alcohol consumption. "As a common risk factor of liver injury, ethanol was confirmed to trigger hepatocyte senescence, a key event participating in the progression of alcoholic liver disease, by decreasing the proteins expression of cellular communication network factor 1 (CCN1) and Sestrin2." (PMID 36499429, 2022).
alveolitis (1 paper, 2018). "Studies of the role of CCN1 in the lung have not been completely explored, although over-expression of CCN1 mediated neutrophilic alveolitis and acute lung injury in mice." (PMID 28638955, 2018).
Alzheimer disease (1 paper, 2026). A progressive, neurodegenerative disease characterized by loss of function and death of nerve cells in several areas of the brain leading to loss of cognitive function such as memory and language. "While elevated in brains of Alzheimer's disease (AD) models and patients, CCN1/Cyr61 levels in cerebrospinal fluid (CSF) remain unclear." (PMID 42305617, 2026).
arteriosclerosis (1 paper, 2023). A vascular disorder characterized by thickening and hardening of the walls of the arteries. "Extracellular protein CCN1 (also called Cyr61, Cysteine-rich angiogenic inducer 61), reported to be up-regulated by Ang II, is an angiogenic-immediate early gene involved in the development and progression of arteriosclerosis." (PMID 37446114, 2023).
astroglioma (1 paper, 2020). "In this study, we found that ZIKV also enhanced the expression of CCN1 in the astroglioma cell line CCF-STTG1." (PMID 31957543, 2020).
bacteremia (1 paper, 2020). "Remarkably, Ccn1ΔMyeloid mice exhibited 100% mortality within 5 days, whereas 60% of Ccn1flox/flox mice survived at least 10 days, showing that myeloid expression of Ccn1 strongly protects against S. aureus bacteremia." (PMID 32144270, 2020).
brain tumours (1 paper, 2021). "To obtain an overview of CCN1 expression in different types and grades of brain tumours, we employed a commercially available TMA assay." (PMID 35052688, 2021). "As the observed increases in CCN1 levels are considerable, the use of larger sample sizes and further investigations could prove CCN1 to be a potential blood biomarker for the monitoring of brain tumour patients to predict disease recurrence and help adapt further treatment." (PMID 35052688, 2021).
cardiac hypertrophy (1 paper, 2025). "As we know, cardiac hypertrophy and fibrosis can result in heart dysfunction; to explore the potential role of CCN1 in cardiac remodeling in mice undergoing 5/6 Nx, we performed H&E, Masson's staining, and Sirius red staining for cardiac histological analysis." (PMID 40225592, 2025).
cartilage disorders (1 paper, 2024). "Regarding the similar role of CCL2 in the pathogenesis of RA and OA, CCN1 inhibition could serve as a potential strategy via reducing the CCL2/CCR2 axis-mediated inflammation in these bone and cartilage disorders." (PMID 39076996, 2024).
Cerebral ischemia (1 paper, 2024). Restriction of arterial blood supply to the brain associated with insufficient oxygenation to support the metabolic requirements of the tissue. "In addition, the improvement of cerebral ischemia injury-induced BBB by Dex was achieved by up-regulating CCN1." (PMID 38364236, 2024). "Dex suppressed cerebral ischemia injury, increased tight junction protein expression, improved the memory ability and neurological function of MCAO rats through targeting CCN1." (PMID 38364236, 2024). "If CCN1 is involved in the regulation of Dex in cerebral ischemia injury-induced BBB has not been reported." (PMID 38364236, 2024).
chordoma (1 paper, 2014). Chordomas are rare malignant tumors arising from embryonic remnants of the notochord in axial skeleton. "The expression of the known chordoma marker brachyury (T) and the matricellular proteins CCN1 and CCN2 were first assessed in U-CH1 cells." (PMID 25541962, 2014). "Through gene expression analysis, we detected expression of CCN1, CCN2, CCN3 and CCN5 in U-CH1 cells under basal conditions, and demonstrate increased expression of CCN3 and CCN5 by chordoma cells in hypoxia." (PMID 25541962, 2014).
chronic asthma (1 paper, 2026). An asthma that is characterized by the development of persistent airway inflammation and recurrent attacks of breathlessness and wheezing, which vary in severity and frequency. "To investigate its functional role in vivo, we utilized a murine model of ovalbumin (OVA)-induced chronic asthma, where the effects of CCN1 were interrogated using both shRNA-mediated knockdown and intranasal administration of recombinant protein." (PMID 41559741, 2026).
chronic cystitis (1 paper, 2024). Recurrent infections of the urinary bladder. "Melatonin is a promising new treatment for chronic cystitis and bladder fibrosis, and CCN1 serves as a key therapeutic target." (PMID 38478501, 2024).
chronic heart failure (1 paper, 2025). "Previous studies have shown that CCN1 is expressed at high levels in chronic heart failure and myocardial remodeling, and the expression of CCN1 in muscle tissue increases with age." (PMID 40225592, 2025). "Additionally, an increase in CCN1 expression is observed in chronic heart failure and myocardial remodeling tissues." (PMID 40225592, 2025).
chronic myeloid leukemia (1 paper, 2025). "The response to imatinib in chronic myeloid leukemia can be regulated by CCN1 through the NF-κB/Bcl-2 pathway." (PMID 40234387, 2025).
COVID-19 (1 paper, 2020). A disease caused by infection with severe acute respiratory syndrome coronavirus 2. "Considering the role of CCN1 which is known to be involved in viral toxicity and inflammation, hiPSC-NS/PCs could provide an excellent model for COVID-19-associated CNS disorders from the aspect of SARS-CoV-2 infection-ACE2-CCN1 axis." (PMID 32934757, 2020). "Thus, CCN1-induced production/secretion of these inflammatory cytokines might constitute the basis of the enhanced inflammation in various organs, including the lung, gut, and CNS, and cytokine storms associated with COVID-19." (PMID 32934757, 2020). "As a first step to develop a new model system for COVID-19-associated CNS disorders in vitro and to investigate the possible involvement of CCN1, we investigated expression of ACE2 and CCN1 in neural stem/progenitor cells (NS/PCs) derived from human-induced pluripotent stem cells (hiPSCs) in vitro." (PMID 32934757, 2020). "Nonetheless, our findings suggest that the damage to the CNS caused by COVID-19 might be reduced by suppressing expression of CCN1, which may thus aid in the development of a therapeutic target for COVID-19-related CNS disorders." (PMID 32934757, 2020). "Therefore, GSI (especially, Compound 34) may thus be neuroprotective and have a therapeutic effect on COVID-19-associated CNS disorder by regulating the pathophysiology of SARS-CoV-2 infection and virulence through suppressing the CCN1 expression JNK signaling." (PMID 32934757, 2020).
gastric ulcer (1 paper, 2012). An ulcerated lesion in the mucosal surface of the stomach. "Our recent study demonstrates that CCN1 can induce a transient epithelial-mesenchymal transition during gastric ulcer healing to facilitate the process of re-epithelialization." (PMID 22701179, 2012).
HCMV infection (1 paper, 2025). "We confirmed alterations in expression levels at the protein level for the classic TEAD1 targets Thrombospondin 1 (THBS1) and Cellular Communication Network Factor 1 (CCN1), both of which were substantially downregulated upon HCMV infection." (PMID 40928347, 2025).
hemangioma (1 paper, 2025). A benign vascular lesion characterized by the formation of capillary-sized or cavernous vascular channels. "The study revealed that hypoxia significantly increases the production of Cyr61/CCN1 in HemECs in a time-dependent manner, and this upregulation further enhances angiogenesis by inducing VEGFA in HemSCs (hemangioma-derived stem cells)." (PMID 40443737, 2025).
Hepatic steatosis (1 paper, 2020). Steatosis is a term used to denote lipid accumulation within hepatocytes. "Here, we showed that CCN1 upregulation was associated with fatty livers and that CCN1 has a positive regulating effect on hepatic steatosis and the inflammatory response in NASH." (PMID 32081971, 2020). "Consistently, haematoxylin and eosin (H&E) staining and oil red O staining showed a significant increase in hepatic steatosis in MCD/Ad-CCN1 mice (32% ± 4%) compared with MCD/Ad-GFP controls (15% ± 2%)." (PMID 32081971, 2020).
Hepatitis (1 paper, 2022). Inflammation of the liver. "We then used the CCN1 conditional knockout (CCN1fl/flCre+) mice to establish ConA induced hepatitis mice model." (PMID 35547732, 2022). "In ConA induced hepatitis mice model, CCN1 conditional knockout (CCN1fl/flCre+) attenuated inflammation by reducing ALT/AST level and IL-6 expression." (PMID 35547732, 2022).
Hypercholesterolemia (1 paper, 2024). An increased concentration of cholesterol in the blood. "Transcriptomic analysis highlighted that paternal hypercholesterolemia stimulated proatherogenic genes, including Ccn1 and Ccn2, in the intima of female offspring." (PMID 39253968, 2024).
hyperlipidemia (1 paper, 2021). "Therefore, ApoE−/− mice were used to study the effects of hyperlipidemia on the expression of CCN1 in retinal vascular tissue." (PMID 34458333, 2021).
injury (1 paper, 2025). Damage inflicted on the body as the direct or indirect result of an external force, with or without disruption of structural continuity. "Cellular communication network factor 1 (CCN1), a secreted matricellular protein and early biomarker of AKI, may regulate macrophage function during kidney injury." (PMID 41422302, 2025).
Lewis lung carcinoma (1 paper, 2019). "To address the role of CCN1 in pathological angiogenesis, we used an allograft Lewis lung carcinoma (LLC) tumour model in EC-specific Ccn1-TG mice." (PMID 31429823, 2019).
macular edema (1 paper, 2024). "No elevated circulating CCN1 level was observed in DR patients with neovascular, macular edema or microaneurysms." (PMID 38755602, 2024).
Myocardial fibrosis (1 paper, 2025). "CCN1 silencing or MAPK pathway inhibition also decreased the expression of myocardial fibrosis and hypertrophy markers in H9c2 cells, while MAPK-related agonist partly reversed the effect of CCN1 inhibition." (PMID 40225592, 2025). "Interestingly, specific knockdown of CCN1 reversed the decline in cardiac function and reduced myocardial fibrosis and hypertrophy in mice with CKD, and the same tendency existed in H9c2 cells treated with serum from mice with CKD." (PMID 40225592, 2025).
premature ovarian failure (1 paper, 2024). "Rats with premature ovarian failure have lower levels of Cysteine-rich 61 (CYR61; also known as CCN1) in their GCs." (PMID 39026050, 2024).
retinitis pigmentosa (1 paper, 2015). Retinitis pigmentosa (RP) is an inherited retinal dystrophy leading to progressive loss of the photoreceptors and retinal pigment epithelium and resulting in blindness usually after several decades. "In disagreement with the results that were obtained in the retinitis pigmentosa model, CCN1 treatment in pure porcine RMG cultures stimulated not only the MAPK/Erk and JAK/Stat pathways but also the PI3K/Akt pathway, whereas it led to activation of the PI3K/Akt and MAPK/Erk pathways in RPE cultures." (PMID 26157362, 2015). "Thus, the neuroprotective and pro-survival activity of CCN1 was studied in a mouse model of retinitis pigmentosa." (PMID 26157362, 2015). "The authors showed that CCN1 activates the mitogen-activated protein kinase (MAPK)/Erk and Janus-associated kinase (JAK)/Stat pathways but not PI3K/Akt pathway in retinal explants from retinitis pigmentosa mice." (PMID 26157362, 2015).
sarcopenia (1 paper, 2021). Progressive decline in muscle mass due to aging which results in decreased functional capacity of muscles. "Furthermore, treatment of MPCs with CCN1/CYR61 induces the expression of senescence-associated β-galactosidase, a known marker for cellular senescence that can be linked to CCN1/CYR61 role in aging-related sarcopenia." (PMID 34063397, 2021).
skin aging (1 paper, 2023). The gradual irreversible changes in structure of skin that occur as a result of the passage of time.. "The role of the CCN1 protein (also known as CYR61) in human skin aging has gained significant attention in recent years." (PMID 38002296, 2023).
systemic sclerosis (1 paper, 2018). A chronic disorder, possibly autoimmune, marked by excessive production of collagen which results in hardening and thickening of body tissues. "In contrast to ERG, the function of FLI1 is less-characterized in ECs; its ablation results in upregulation of CTSL and CXCL6 and downregulation of CXCL5 and CCN1 in the context of systemic sclerosis." (PMID 30500808, 2018).
type-I diabetes (1 paper, 2021). "For example, CCN1/CYR61 and CCN2/CTGF are basally increased in a mouse model for type-I diabetes, which presents myofiber atrophy and reduced capillary number to fiber ratio, evidencing decreased blood supply to the skeletal muscle." (PMID 34063397, 2021).
ZIKV infection (1 paper, 2020). "Therefore, CCF-STTG1 cells were used as an in vitro model to investigate the mechanism underlying ZIKV infection-mediated CCN1 expression in astrocytes." (PMID 31957543, 2020). "In this study, we demonstrate that ZIKV infection up-regulates CCN1 expression in astrocytes, thus promoting intracellular viral replication." (PMID 31957543, 2020). "ZIKV-E protein was detected using western blot to investigate the effects of CCN1 on ZIKV infection." (PMID 31957543, 2020). "In conclusion, we demonstrated that ZIKV infection up-regulates CCN1 protein in human astrocytes and that the NS3-CaMKIIα-CREB pathway is critical for CCN1 up-regulation." (PMID 31957543, 2020). "This suggests that CCN1 downstream signaling is important for the enhancement of ZIKV infection." (PMID 31957543, 2020). "This indicates that ZIKV infection up-regulated CCN1 expression in mouse astrocytes in vivo." (PMID 31957543, 2020).